SIRT1 (sirtuin 1)
Diseases named in the same sentence as SIRT1 in open-access papers (continued):
Sharing a sentence is not in itself a finding about the gene and the disease.
tumor (continued). "They need a functional NAD+-Sirt1 Axis to exert an anti-tumor response, which research proved that the anti-CD38 antibody could enhance the inhibition of tumor." (PMID 35978433, 2022). "However, melatonin is well-known as an antioxidant and anti-apoptotic agent in most non-tumor cells and acts as a SIRT1-upregulating agent under senescent conditions." (PMID 35795579, 2022). "As already mentioned in this work, SIRT1 can be a tumor promoter or a tumor suppressor." (PMID 36499440, 2022). "In fact, SIRT1 expression is negatively correlated with tumor TNM stage and lymphatic invasion." (PMID 36499440, 2022). "Indeed, SIRT1 directly influences tumor progression, metastasis, resistance to apoptosis, autophagy, DNA repair, and other oncogenic mechanisms." (PMID 35806366, 2022). "Furthermore, a high frequency of SIRT1 overexpression was reported during tumor progression in endometrial carcinoma." (PMID 35853978, 2022). "We also identified the tumor-suppressive role of MOF via targeting SIRT1." (PMID 35252011, 2022). "The PI3K/Akt/mTOR pathway is involved in some neurodegenerative and tumor processes; moreover, mTOR has a significant role in the modulation of autophagy induction and is inversely related to SIRT1 (the latter is involved in neurodegenerative and tumor processes)." (PMID 35741059, 2022). "Six studies reported the relationship between SIRT1 and tumor size, age, and gender in ESCC." (PMID 35350833, 2022). "SIRT1 expression was very low in the 67NR groups and in the tumor-free groups." (PMID 36142156, 2022). "Our findings indicated that MOF serves as a tumor suppressor via regulation of SIRT1 in the development and progression of RCC, and MOF might be a potent biomarker for diagnosis and prognosis prediction of RCC patients." (PMID 35252011, 2022). "This indicates a tumor suppressor role of miR-22 through the negative regulation of SIRT1." (PMID 36291902, 2022). "Many studies suggest that SIRT1 also acts as a tumour suppressor." (PMID 36078035, 2022). "However, some studies have found that NAMPT can also inhibit tumor migration and metastasis by regulating SIRT-1, indicating that the mechanism remains to be further explored." (PMID 35906622, 2022). "Our findings show that SIRT1 could affect the target genes of FoxO proteins and that the tumor cell can fight to survive." (PMID 36142156, 2022). "However, SIRT1 is reported to have contradictory functions acting as a tumor suppressor, as well as an oncogenic protein." (PMID 36080304, 2022). "Several studies have revealed that SIRT1 inhibitors inhibit tumor formation." (PMID 35163511, 2022). "Moreover, treatment of JBSNF-000088 significantly decreased the expression of SIRT1 and c-myc in xenograft tumor." (PMID 35387964, 2022). "SIRT-1/2/4/6/7 acts as a tumor suppressor mainly through deacetylation." (PMID 35906622, 2022). "Immunolocalization of SIRT1 was altered in tumor cells treated with AntiGan." (PMID 35054489, 2022). "Therefore, depending on cell conditions and the stage of the disease, SIRT1 plays a regulatory role either towards tumor progression or suppression, balancing the process of oncogenesis." (PMID 36361680, 2022). "Similar levels of SIRT1 were observed in non-tumor tissues from both stages and stage III tumors." (PMID 35205159, 2022).
tumor (continued). "The increased expression of SIRT1 is correlated with tumor treatment and prognosis." (PMID 35432540, 2022). "Thus, 3 out of 11 cases displayed much lower levels of SIRT1 and P‐SIRT1Ser27 than the other tumor specimens." (PMID 34826187, 2022). "In NIH3T3 cells, SIRT1 causes ubiquitination and degradation of FOXO3, a FOXO transcription factor family member that can play a crucial role in tumor suppression and metabolism and may act as oncogene." (PMID 35136826, 2022). "SIRT1 and P‐SIRT1Ser27 were barely detectable in some tumor specimens." (PMID 34826187, 2022). "In support of this hypothesis, it was recently shown that the CD38-NAD+-Sirt1 axis regulates immunotherapeutic anti-tumor T cell responses." (PMID 35281060, 2022). "SIRT1 plays a dual role of tumor suppressor or tumor promoter in different tumors." (PMID 36551694, 2022). "First, surface plasmon resonance or other methods need to be conducted to confirm the direct interaction of elaiophylin and SIRT1, and then an orthotopic transplanted mouse model needs to be constructed in the further study which is closer to the environment of the tumor." (PMID 36497294, 2022). "However, SIRT1 can function as both a tumor promoter and tumor suppressor simultaneously, depending on the immediate microenvironment." (PMID 35548580, 2022). "Conversely, SIRT1 has also been shown to be involved in cell proliferation inhibition, G1 cell cycle arrest, migration and invasion, and apoptosis induction in vitro, and tumor growth and metastasis inhibition in vivo." (PMID 36358890, 2022). "Indeed, SiRT-1 has been reported to play a key role in tumorigenesis, as an oncogene or tumor suppressor." (PMID 36301384, 2022). "Heterozygous deletion of SIRT1 increased c-Myc expression, and thereby promoted tumor growth." (PMID 34650436, 2021). "Additionally, a correlation between SIRT1 expression, tumor progression, and prognosis has also been found in patients with ChS." (PMID 33804155, 2021). "Changes of expression or activity of SIRT1 can result in functional variations of the neuroendocrine system, inflammatory and tumor microenvironment through driving proteins, cargos in exocytosis vesicles and exosomes secreting into extracellular microenvironment." (PMID 33390835, 2021). "However, SIRT1 can function as a tumor suppressor in the context of the MLL mutant molecular subtype of AML via deacetylation of local H3K9 histones." (PMID 34407842, 2021). "SIRT1 plays a dual role as a tumor promoter as well as a tumor suppressor." (PMID 33435147, 2021). "SIRT1 also can promote tumor cell growth with autophagy activity that requires mTOR inhibition, suggesting that both SIRT1 and autophagy pathways can be targets to control tumor cell growth." (PMID 34356626, 2021). "Moreover, the expression of sirtuin 1 (SIRT1), a deacetylase in tumor cells was upregulated by FBXW11 via regulating HIC1 expression." (PMID 34642302, 2021). "Besides, a class III histone deacetylase, silent mating type information regulation 1 (SIRT1), is augmented in tumor tissues, in addition to correlating with metastasis of GC in advanced lymph node." (PMID 35153766, 2021). "At present, the research of Sirt1 in tumor immunity is gradually in-depth." (PMID 34880761, 2021). "Similarly, SIRT1 enzyme activity was significantly diminished in tumor-bearing mice compared to that in normal mice, which was also increased in the dunnione-treated groups." (PMID 34769515, 2021). "The study further showed that knockdown of SIRT1 or PGC1α sensitized the tumour cells to the drug treatment, suggesting that the SIRT1/PGC1α is a novel pathway of drug resistance that may be targeted for therapy." (PMID 34733591, 2021).
tumor (continued). "Specifically, we will show that KCNQ1OT1 and miR-124 mediate RB cell progression possibly via regulating SP1 expression and silent information regulator 1 (SIRT1)/c-Jun N-terminal kinase (JNK) signaling, which are strongly associated with tumor cell proliferation, apoptosis, and migration." (PMID 33345272, 2021). "However, two contradictory roles have been considered for SIRT1 including tumor promoter and tumor suppressor." (PMID 33630973, 2021). "Additionally, in vivo studies showed that the use of metformin resulted in reduced tumor growth in a SIRT1-dependent manner." (PMID 34769241, 2021). "Moreover, SIRT1 is a negative regulator of tumor metastasis that upregulate E-cadherin and downregulate the mesenchymal markers, N-cadherin and vimentin levels." (PMID 33922238, 2021). "SIRT1 could serve as a tumor suppressor as it deacetylates and inactivates various tumor-promoting transcriptional factors." (PMID 34650436, 2021). "The activation of STAT3/MMP13 signaling after SIRT1 depletion suggests that SIRT1 may work as a tumor suppressor." (PMID 34769241, 2021). "The same mechanisms are involved in the skin carcinogenesis, however, SIRT1 may serve as tumor suppressor or oncogene, depending on the gene dosage and downstream pathways." (PMID 33917352, 2021). "As a result, overexpression of p62 in liver reversed the decline of tumor burden in Sirt1 CKO mice." (PMID 33854041, 2021). "Dunnione increases the cellular NAD+ levels in lung tissues of tumor-bearing mice to restore the declining sirtuin 1 (SIRT1) activity, thus deacetylating nuclear factor-kappa B (NF-κB) and preventing the overexpression of tissue factor in bronchial epithelial and vascular endothelial cells." (PMID 34769515, 2021). "Further research is needed on the specific regulation details of Sirt1 in tumor microenvironment." (PMID 34880761, 2021). "Collecting this observation, autophagic process is modulated via SIRT1 or other mediators that might play an essential role in tumor progression via modulating EMT as well as tumor cell invasion." (PMID 35153766, 2021). "By association with USP22 in the SAGA complex, SIRT1 targets protein deacetylation on the structures of their histones or non-histones to facilitate tumour progression." (PMID 34226501, 2021). "i.e., miR-155, miR-17-92 and miR-21 act as oncogenes by altering the expression levels of MYC, SHIP and FOXO1, respectively, conversely; miR-34a, mir-144 and miR-181a act as tumor suppressors by altering the expression levels of SIRT1, BCL6 and CARD11, respectively." (PMID 34679437, 2021). "SIRT1 presents lower expression and is considered as a potential tumor suppressor in OSCC." (PMID 34384029, 2021). "However, Sirt1 mRNA levels are similar in HCC and non-tumor adjacent tissues, suggesting that Sirt1 overexpression was mediated by post-transcriptional mechanism in HCC36." (PMID 33854041, 2021). "Moreover, SIRT1 overexpression in HHUA cells accelerated tumor growth and cisplatin resistance in nude mice, and EX527 significantly suppressed the growth of tumors of HHUA and HEC1B cells." (PMID 33435147, 2021). "Interestingly, that expression of GRHL3 significantly reduced in tumor tissues overexpressing SIRT1." (PMID 34163012, 2021). "In contrast, some studies reported SIRT1 as a tumor activator." (PMID 34650436, 2021). "At 25 months of age, SIRT1 + 6-tg mice exhibited significantly fewer neoplasms." (PMID 34050173, 2021). "SIRT1 is also involved in cell regulatory mechanisms and can serve as tumor promotor or suppressor." (PMID 32388637, 2020). "Furthermore, CHC treatment only display a very mild effect in CAM-developed tumor growth, as well as in SIRT1 and H3K9 acetylation levels." (PMID 32340156, 2020). "However, the molecular mechanism of the tumor-suppressive role of SIRT1 in RAS-driven tumorigenesis has yet to be fully elucidated." (PMID 32276460, 2020).
tumor (continued). "Its effect on advanced stage tumors may be heterogeneous, depending on whether a tumor has evolved to rely on SirT1 for survival." (PMID 32366137, 2020). "SIRT1 may have contradictory roles in promoting or suppressing in different cell contexts or types of tumor development." (PMID 31956359, 2020). "Based on these reports, this study sought to determine whether SIRT1 can regulate the tumor-inhibiting activity of HINT1 through deacetylation in colon and melanoma cancer cells." (PMID 32636443, 2020). "Interestingly, SIRT1 has been shown to play a dual role in tumorigenesis, acting either as an oncogene or tumor suppressor gene according to the tumor context." (PMID 32340156, 2020). "Several studies suggest that Sirt1 can act both as a tumor promoter and as a tumor suppressor." (PMID 33203121, 2020). "Some of the controversy regarding whether SIRT1 acts in an oncogenic or tumor suppressive manner may be better reconciled as we consider the difference in multiple experimental designs." (PMID 33330467, 2020). "Taken together, these results indicate that reversible acetylation of HINT1 by CBP and SIRT1 may be a major mechanism for regulation of HINT1 tumor-suppressive activity." (PMID 32636443, 2020). "Interestingly, melatonin-evoked decline in SIRT1 level was found in case of tumor cells that also represent abnormal energy metabolism, similar to that characteristic of hypoxic conditions." (PMID 33519498, 2020). "Similarly, other reports confirmed that SIRT1 inhibition had a direct or indirect role in the control of tumor cell growth and metastasis." (PMID 32607257, 2020). "SIRT1 was initially identified as a nuclear protein, but subsequent experiments showed that it can also shuttle into the cytoplasm during neuronal differentiation, tumor progression, and apoptosis." (PMID 33269110, 2020). "Based on these reports, we suggest that SIRT1 may have a direct/indirect role in tumor promotion/suppression." (PMID 32607257, 2020). "In general, our work suggests that SIRT1 may serve as the mediate to promote hepatocarcinogenesis and inhibition of SIRT1 may block the tumor process mediated by HBx." (PMID 32714081, 2020). "Strikingly, only parent resveratrol had appreciably any effect on sirtuin activity to suggest a SIRT1-independent role in growth inhibition of the aspirin-resveratrol derivatives, or protection from inflammation injury or anti-tumor effect as observed in this study." (PMID 32847114, 2020). "Additionally, tumor-bearing mice were used to verify that Sirt1 overexpression confers Adriamycin resistance in vivo after chemotherapy." (PMID 32570218, 2020). "An overexpression of SIRT1 had been recognized in several tumor cells, including HCCs." (PMID 32607257, 2020). "Besides, overexpression of Sirt1 in mesenchymal stem cells inhibits PCa cells growth prostate growth through recruiting natural killer cells and macrophages in tumor micro-environment." (PMID 32431616, 2020). "Similarly, betulinic acid derivative (B10) increased FOXO3a transcription and reduced SIRT1 expression leading to induced apoptosis in vitro and reduced in vivo tumor growth and hence B10 is a novel therapeutic candidate for glioma treatment." (PMID 33330467, 2020). "SIRT4 inhibits mitochondrial metabolism and SIRT1 expression to reduce tumor energy metabolism." (PMID 33585187, 2020). "Although several sirtuins can function as both tumor promoters and suppressors, SIRT1/3/5-7 blockade may aid in effective chemotherapy, as described in the next section." (PMID 31956359, 2020). "Therefore, over-expression of SIRT1, 2, and 4 in tumor tissues provided new promising biomarkers and drug targets for clinical HCC treatment." (PMID 33093847, 2020).
tumor (continued). "The role of SIRT1 in tumors is still under debate since it could act as tumor suppressor or tumor promoter depending on the cellular environment and specific signaling pathways." (PMID 32655835, 2020). "Moreover, the level of SIRT1 increased with the increasing tumor stage and primary tumor, which indicated ARGs were involved in the progression of EAC and it is essential to increase our understanding of the pathways between autophagy and clinical features." (PMID 32998713, 2020). "Regarding β-Catenin, another tumor suppressor and part of the Wnt-pathway, positive membranous and negative nuclear staining correlated to better survival rates, as well as SIRT1 expression." (PMID 32388637, 2020). "Studies on the role of SIRT1 as a tumor suppressor or oncogene are controversial and may depend on the tumor type." (PMID 32878301, 2020). "However, the potential role of SIRT1 on the AVC-mediated anti-inflammatory effect in lung tissue during tumor development remains elusive." (PMID 32489686, 2020). "Sirt1 was first recognized as an oncogene, as overexpression of Sirt1 could repress expression and/or activity of several tumor suppressor genes and proteins that are involved in DNA repair." (PMID 32698385, 2020). "Moreover, SIRT1 also acts as a tumor suppressor directly or by repressing other oncogenes (e.g., Myc)." (PMID 32727075, 2020). "Furthermore, our in vitro data supported the finding that SIRT1 overexpression markedly hampered HRAS-induced tumorigenic activities, indicating SIRT1 as a tumor suppressor in the oncogenic RAS activation setting as well." (PMID 32276460, 2020). "Additionally, we found BECN1, DAPK1, VAMP7 and SIRT1 genes were correlated significantly with survival status, gender, primary tumor and tumor stage (all P < 0.05)." (PMID 32998713, 2020). "In addition, Sirt1 protein expression was also detected in DLBCL tumor tissues and DLBCL cell lines using western blotting." (PMID 32570218, 2020). "Consistent with the in vitro results, data from in vivo limiting dilution assays showed that mice harboring SIRT1-overexpressing SGC-7901 cells showed impaired tumor-initiating ability, whereas mice harboring SIRT1-knockdown SGC-7901 cells exhibited accelerated tumor formation." (PMID 32051395, 2020). "In cattle, the beneficial effects of dietary RES might derive in part by preventing mitochondrial ATP synthesis in tumor cells, thereby inducing apoptosis via the Sirt1-PGC1α-PPARα pathway." (PMID 33362577, 2020). "Therefore, in the present study, we aimed to extend this work by investigating the association between SIRT1 polymorphisms and CRC by MSI and CIMP status in the NLCS using 7.3 years of follow up (excluding the first 2.3 years), where tumour DNA was available." (PMID 32098999, 2020). "In conclusion, the dialog between MSCs and tumor cells in FAP-associated DT tissue microenvironment could lead to β-catenin deacetylation driven by SIRT1, promoting Wnt/β-catenin signaling cascade in this tumor." (PMID 32655835, 2020). "By multiple interactions, SIRT1 can act either as tumor promotor or as tumor suppressor." (PMID 32388637, 2020). "Like Sirt1-3, Sirt5 was shown to have dual tumor suppressor and tumor promoter activities." (PMID 32698385, 2020). "Therefore, the precise tumorigenic and anti-tumorigenic functions of SIRT1 are highly dependent on the genetic context of the cell or tumor in question." (PMID 31598701, 2019). "Sirtuin 1 (SIRT1) exerts diverse effects on tumor cells as an oncoprotein or tumor suppressor." (PMID 31526370, 2019).